Y_RNA (Y RNA )
Gene: Miscellaneous RNA gene on chromosome 22 (41,065,554 to 41,065,646, reverse strand). Ensembl gene ENSG00000199515.
Homologues: Orthologues: chimpanzee Y_RNA (99% identical). Paralogues in human: RNY4 (85% identical), RNY4P10 (85% identical), Y_RNA (85% identical), Y_RNA (84% identical), RNY4P6 (83% identical), Y_RNA (82% identical), RNY4P13 (81% identical), RNY4P14 (81% identical), RNY4P7 (81% identical), Y_RNA (81% identical), RNY4P24 (80% identical), Y_RNA (80% identical), and 88 more.